IL34 (interleukin 34)
Diseases named in the same sentence as IL34 in open-access papers (continued):
Sharing a sentence is not in itself a finding about the gene and the disease.
metastatic melanoma (2 papers, 2018 to 2023). A melanoma that has spread from its primary site to another anatomic site. "Nivolumab-resistant metastatic melanoma showed an increase in the expression of IL-34 associated with higher M2 macrophage infiltration." (PMID 36798830, 2023).
myocardial infarction (2 papers, 2021 to 2025). Gross necrosis of the myocardium, as a result of interruption of the blood supply to the area, as in coronary thrombosis. "However, ab12 partially decreased the IL-34-mediated increase in myocardial infarction size (0.53 ± 0.022, p<0.05), serum cTnI (60.96 ± 2.92 ng/ml, p<0.05) and serum CK-Mb (2215.60 ± 60.75 ng/mL, p<0.05) levels." (PMID 39883639, 2025). "Accumulating studies have shown that the IL-34 concentration is significantly increased in patients with CAD, and this increase is positively correlated with the severity of acute myocardial infarction." (PMID 39883639, 2025).
neuroblastoma (2 papers, 2020). Neuroblastoma (NB) is the most common solid, extracranial childhood tumor. "A recent study found that calcitriol could induce IL-34 in a human neuroblastoma cell line (SH-SY5Y), and identified a putative VDRE site in the IL-34 promoter, supporting the hypothesis that vitamin D can positively regulate IL-34 expression." (PMID 32082243, 2020).
osteopetrosis (2 papers, 2021 to 2025). Osteopetrosis, also known as marble bone disease, is a descriptive term that refers to a group of rare, heritable disorders of the skeleton characterized by increased bone density on radiographs. "Although Il34 mRNA is highly expressed by osteoblasts there was no significant impact of the Il34 mutation on bone density detectable by micro-computed tomography, in contrast to the severe unremitting osteopetrosis observed in Csf1tl/tl rats." (PMID 40533345, 2025). "As already mentioned, in studies using knockout mice for CSF-1 and CSF-1R, IL-34 circumvented the observed osteopetrosis phenotype, suggesting that IL-34 may play a role in osteoclast generation." (PMID 33408768, 2021).
periodontal disease (2 papers, 2013 to 2021). "This is the first study providing evidence for a possible role of IL-34 in periodontal disease, supported by its recently discovered role in other bone-degenerative diseases such as RA." (PMID 24339952, 2013). "The role of IL-34 in periodontal disease, and its expression in gingival fibroblasts is yet unknown." (PMID 24339952, 2013).
renal carcinoma (2 papers, 2022 to 2025). A carcinoma arising from the epithelium of the renal parenchyma or the renal pelvis. "Interleukin-34 (IL34) treatment strongly enhanced hepcidin expression in renal cancer Caki-1 cells." (PMID 36532749, 2022). "In our previous study, we investigated the transcriptomic changes in renal cancer cells during tumor progression in a murine RCC model and identified interleukin-34 (IL34) as a potential driver." (PMID 40538439, 2025).
scrapie (2 papers, 2017 to 2019). A fatal disease of the nervous system in sheep and goats, characterized by pruritus, debility, and locomotor incoordination. "However, this explanation leaves open the question of what caused the decrease in scrapie survival in the IL-34−/− mice that had normal levels of activated microglia." (PMID 30650564, 2019).
squamous cell carcinoma (2 papers, 2018 to 2024). A carcinoma arising from squamous epithelial cells. "Squamous cell carcinoma of the cervix, head and neck, oesophagus and lung demonstrate downregulation of IL34, which is associated with poor survival, and with alterations in LC spatial organisation and function." (PMID 39619016, 2024). "This study aimed to uncover mechanisms of alteration of IL34 and LC function in squamous cell carcinoma (SCC)." (PMID 39619016, 2024). "This study shows that low expression of IL34 determines poor survival in squamous cell carcinomas." (PMID 39619016, 2024).
Stroke (2 papers, 2020 to 2022). Sudden impairment of blood flow to a part of the brain due to occlusion or rupture of an artery to the brain. "Our results suggested that IL-34 and IL-38 were independently associated with stroke and all-cause mortality in patients with AF." (PMID 36698935, 2022). "During the median follow-up time of 28 (IQR: 27, 29) months, the higher levels of IL-34 were associated with a lower risk of stroke, and the higher levels of IL-38 were associated with an increased risk of all-cause death (all adjusted P < 0.05)." (PMID 36698935, 2022). "However, it was noteworthy that AF patients with lower IL-34 levels have a higher risk of stroke, which seemed counterintuitive to its pro-inflammatory role." (PMID 36698935, 2022). "We found that IL-34 [hazard ratio (HR): 0.36, 95% confidence interval (CI): 0.17–0.78, P = 0.010] and hs-cTnT (HR: 3.09, 95% CI: 1.33−7.19, P = 0.009) were independently correlated with the risk of stroke." (PMID 36698935, 2022). "In conclusion, serum IL-34 and IL-38 may serve as biomarkers of prognostic evaluation for stroke and all-cause mortality in patients with AF." (PMID 36698935, 2022). "In our findings, the C-statistic of stroke prediction model integrated IL-34 and/or hs-cTnT were all superior to the original model, and NRI of the CHA2DS2-VASc score combined with hs-cTnT had a significantly improved." (PMID 36698935, 2022). "Therefore, the issue of whether IL-34 is beneficial or harmful in stroke-attacked AF patients merits further study." (PMID 36698935, 2022). "For predicting stroke, the clinical net benefit of modified CHA2DS2-VASc score adding IL-34 and hs-cTnT was slightly better than other scores." (PMID 36698935, 2022).
acute monocytic leukemia (1 paper, 2021). Acute monoblastic leukemia (AML-M5), is one of the most common subtypes of acute myeloid leukemia (AML) that is either comprised of more than 80% of monoblasts (AML-M5a) or 30-80% monoblasts with (pro)monocytic differentiation (AML-M5b). "We previously demonstrated that IL-34 promoted the proliferation and colony formation of human acute monocytic leukemia (AMoL) cells." (PMID 35402828, 2021).
adult T-cell leukemia/lymphoma (1 paper, 2020). A peripheral (mature) T-cell neoplasm linked to the human T-cell leukemia virus type 1 (HTLV-1), adult T-cell leukemia/lymphoma is endemic in several regions of the world, in particular Japan, the Caribbean, and parts of Central Africa. "Finally, in adult T-cell leukemia/lymphoma (ATLL), IL-34 and M-CSF-1 co-expression was found to correlate with tumor aggressiveness." (PMID 31968663, 2020).
autoimmune thyroiditis (1 paper, 2018). "Here, we demonstrate that IL-34 is expressed on thyroid follicular epithelial cells and that IL-34 expression is significantly reduced in thyroid tissue in patients with HT and spontaneous autoimmune thyroiditis (SAT) models." (PMID 30405534, 2018).
Brain atrophy (1 paper, 2025). Partial or complete wasting (loss) of brain tissue that was once present. "Thus, while T2LL-dysproportional brain atrophy and SC injury share proteomic signatures, pwMS with disproportional SC injury have additional CSF proteomic changes suggestive of sustained ICs formation and disrupted IL34/CSF1 signaling axis." (PMID 41339376, 2025).
brain cancer (1 paper, 2015). A primary or metastatic malignant neoplasm affecting the brain. "However, in the brain cancer cases, a higher expression of the IL-34 gene was related to poor survival." (PMID 25395235, 2015).
chronic hepatitis (1 paper, 2018). An active inflammatory process affecting the liver for more than six months. "On the other hand, IL-34 has been found overexpressed in chronic hepatitis, inducing pro-fibrotic macrophages to release transforming growth factor β, platelet-derived growth factor, as well as galectin-3." (PMID 30050466, 2018).
chronic hepatitis C virus infection (1 paper, 2025). Chronic form of hepatitis C infection. "In contrast, M-CSF and IL-34, which facilitate macrophage survival and differentiation and mediate their biological activity via binding to and signaling through the M-CSF receptor (c-fms/CD115), are produced at high levels in chronic hepatitis C virus infection." (PMID 40507836, 2025).
coronary stenosis (1 paper, 2018). Narrowing of the coronary artery lumen diameter. "IL-34 may take part in the process of ischemic HF via mediating the severity of coronary stenosis, cardiac fibrosis, and inflammatory process; however, the underlying mechanisms remain incompletely understood." (PMID 30050466, 2018). "Furthermore, since ICM is a severe form of end-stage CAD, IL-34 may affect ICM partly through aggravating coronary artery stenosis as it was correlated with the Gensini score." (PMID 30050466, 2018).
demyelination (1 paper, 2025). "In an acute demyelination mouse model, activated astrocytes express multiple ligands, including Cx3cl1, Csf1, Il34, and Gas6, which act on both homeostatic and activated microglia, thereby potentially mediating microglial activation, recruitment, and enhancing their phagocytic activity." (PMID 40292254, 2025).
enthesitis (1 paper, 2022). Inflammation at the site of insertion of ligaments, tendons, and other fibrous structures into bone. "In patients with AS, serum levels of both IL-34 and RANKL were correlated positively with enthesis bone erosion and enthesitis, while only IL-34 was positively correlated with the number of entheses with a power Doppler signal." (PMID 37551285, 2022). "Thus, serum levels of IL-34 could be used as indicator of enthesitis in patients with AS, especially for those with bone erosion." (PMID 37551285, 2022). "In patients with AS, serum levels of IL-34 and RANKL adjusted for age and weight were significantly correlated with enthesitis (0.798, P < 0.01; 0.347, P < 0.05, respectively) and bone erosion (0.822, P < 0.01; 0.368, P < 0.05, respectively)." (PMID 37551285, 2022). "Therefore, we assessed enthesitis and bone erosion with ultrasonography and measured serum levels of IL-34 and RANKL using enzyme-linked immunosorbent assays (ELISA) to determine the correlations between serum levels of IL-34, RANKL, and enthesis lesions in patients with AS." (PMID 37551285, 2022). "In patients with AS, the serum levels of IL-34 and RANKL may be useful indicators of enthesitis, especially bone erosions." (PMID 37551285, 2022). "In patients with AS, serum levels of IL-34 and RANKL may be useful indicators of enthesitis, especially for bone erosions." (PMID 37551285, 2022). "However, to our knowledge, the relationship between enthesitis and bone erosion, and IL-34 and RANKL in AS has not yet been elucidated." (PMID 37551285, 2022).
epithelial dysplasia (1 paper, 2024). "In conclusion, our research highlights that IL34 downregulation is a common occurrence in diseases associated with epithelial dysplasia, including inflammatory skin diseases and various SCCs such as lung, head and neck, cervical and oesophageal SCC." (PMID 39619016, 2024).
gestational diabetes mellitus (1 paper, 2023). "Another study illustrated that IL-34 was elevated in gestational diabetes mellitus and may cause inflammation by targeting GSF-1R." (PMID 36879647, 2023).
Huntington disease (1 paper, 2021). Huntington disease (HD) is a rare neurodegenerative disorder of the central nervous system characterized by unwanted choreatic movements, behavioral and psychiatric disturbances and dementia. "However, it has been also reported that in certain neural disorders, e.g. Huntington disease, IL-34 can induce microglia differentiation with neurotoxic pro-inflammatory properties and production of pro-inflammatory molecules." (PMID 33408768, 2021). "On the other hand, IL-34 may display some neurotoxic effects in Huntington's disease, characterized by high expression of the amyloidogenic fragment of the Huntington protein (mHTTx1)." (PMID 33408768, 2021).
Hydrocephalus (1 paper, 2025). Hydrocephalus is an active distension of the ventricular system of the brain resulting from inadequate passage of CSF from its point of production within the cerebral ventricles to its point of absorption into the systemic circulation. "In mice invalidated for IL34, obtained at an expected frequency (Mendelian inheritance) but with a reduced life expectancy (3 weeks), significant craniofacial dysmorphoses were observed with the presence of hydrocephalus." (PMID 40083929, 2025).
kidney cancer (1 paper, 2019). Primary or metastatic malignant neoplasm involving the kidney. "CSF1 and IL34 are expressed in various tumors (TCGA database) such as kidney cancers." (PMID 31552020, 2019).
kidney inflammation (1 paper, 2024). "Collectively, our research elucidates the pro-inflammatory function and YAP/IL-34/macrophage axis-mediated mechanism of αvβ6 in renal inflammation, providing a solid rationale for the use of αvβ6 inhibition to treat kidney inflammation and fibrosis." (PMID 38844455, 2024).
kidney transplant (1 paper, 2022). A surgical procedure in which one or both kidneys from a donor are implanted into a recipient. "Finally, taking advantage of a biocollection, we investigated the correlation between presence of IL‐34 in the serum and kidney transplant rejection." (PMID 36030499, 2022).
nocardiosis (1 paper, 2020). Nocardiosis is a local (skin, lung, brain) or disseminated (whole body) acute, subacute, or chronic bacterial infection. "Collectively, IL-34 is a promising adjuvant in a DNA vaccine against nocardiosis in fish." (PMID 32231137, 2020).
ovarian failure (1 paper, 2023). "While Csf1a is required and its loss completely blocks ovary-to-testis transition, loss of Il34 only delays it, suggesting that the two ligands contribute differently and that Csf1a is the main driver of ovary-to-testis transformation during ovarian failure." (PMID 37992158, 2023). "Although previously thought to signal primarily through Csf1Ra, which is dispensable for ovarian failure and sex reversal on its own, Il34 was recently shown to also signal through Csf1Rb." (PMID 37992158, 2023). "Consistent with a role for Il34 in promoting oocyte loss, removal of Il34 suppressed ovarian failure of bmp15 mutants, but, unlike loss of Csf1a, eliminating Il34 only delayed the ovary-to-testis transition." (PMID 37992158, 2023).
papillary thyroid cancer (1 paper, 2020). "In this study, we analyzed the expression of IL‐34 in human papillary thyroid cancer (PTC) samples and determined its effects on the proliferation and apoptosis of PTC cells." (PMID 32573824, 2020).
peripheral nerve injury (1 paper, 2016). Injury to a peripheral nerve. "We next asked whether expression of mRNAs for M-CSF, IL-34, GM-, and G-CSF in the spinal cord were affected by peripheral nerve injury using same techniques." (PMID 27071004, 2016).
Pleural effusion (1 paper, 2021). The presence of an excessive amount of fluid in the pleural cavity. "Additionally, cytokines promoting the M2 differentiation, namely IL-34, macrophage colony stimulating factor (M-CSF) and C-C motif chemokine ligand 2 (CCL2) have been found to be elevated in tumor specimens or pleural effusion of MPM patients." (PMID 33562138, 2021).
renal dysfunction (1 paper, 2016). "After adjusting for age, gender, conventional risk factors, and other significant covariates, IL-34 positively correlated with the presence and severity of renal dysfunction (as measured by eGFR and cystatin C) on multivariable linear and logistic regression analysis." (PMID 27982136, 2016). "However, all these studies excluded patients with cardiac dysfunction or renal dysfunction, while our present study included those patients, thus expanding the scope of application of IL-34 as a predictive biomarker for CAD." (PMID 27982136, 2016).
Renal insufficiency (1 paper, 2016). A reduction in the level of performance of the kidneys in areas of function comprising the concentration of urine, removal of wastes, the maintenance of electrolyte balance, homeostasis of blood pressure, and calcium metabolism. "In conclusion, elevated serum IL-34 levels were demonstrated to be independently associated with renal insufficiency and CAD in patients with CHF, regardless of the systolic function." (PMID 27982136, 2016).
retinal diseases (1 paper, 2021). "Another example of IL-34 neuroprotection occurs in retinal diseases such as photoreceptor degeneration disease." (PMID 33408768, 2021).
salivary gland disorder (1 paper, 2018). A disease involving the saliva-secreting gland. "Our findings emphasize the pathological roles of IL-34 as an inflammation amplifier and angiogenic enhancer in inflammatory conditions, such as in salivary gland disorders." (PMID 30002743, 2018).
schwannoma (1 paper, 2019). A benign, usually encapsulated slow growing tumor composed of Schwann cells. "Before applying anti-M-CSF or anti-IL-34 therapy in VS patients, in vivo schwannoma models would be very helpful to further elucidate the biological mechanisms that are involved in the associations observed in this study." (PMID 30580386, 2019).
thyroid carcinomas (1 paper, 2020). "However, the function of IL‐34 in thyroid carcinoma has yet to be investigated." (PMID 32573824, 2020).
vitiligo (1 paper, 2021). Generalized well circumscribed patches of leukoderma that are generally distributed over symmetric body locations and is due to autoimmune destruction of melanocytes. "Therefore, ENST0000460164.1 may act through the ENST0000460164.1/mir-637/IL16 or ENST0000460164.1/mir-637/IL34 axis in vitiligo." (PMID 34941177, 2021). "Therefore, NR-046211.1 may regulate the pathogenesis of vitiligo through NR-046211.1/mir-328/IL1β axis, but NR-046211.1/mir-637/IL16, and NR-046211.1/mir-637/IL34 axis need further confirmation." (PMID 34941177, 2021).